NAALADL1 (N-acetylated alpha-linked acidic dipeptidase like 1)
Description:
Aminopeptidase with broad substrate specificity. Has lower activity with substrates that have Asp or Glu in the P2' position, or Pro in the P3' position. Lacks activity with substrates that have both Pro in the P3' position and Asp or Glu in the P2' position. Lacks carboxypeptidase activity. Lacks dipeptidyl-peptidase IV type activity.
Synonyms: I100; NAALADASEL; HILAP
Tractability: Antibody: UniProt places it where antibodies can reach, with medium confidence; UniProt predicts a signal peptide or a membrane-spanning region; its Gene Ontology location is reachable by antibodies, with medium confidence.
Gene: Protein-coding gene on chromosome 11 (65,044,818 to 65,058,553, reverse strand). Ensembl gene ENSG00000168060.
Subcellular location: Apical cell membrane
Subcellular location (Human Protein Atlas): Cytosol
Gene Ontology:
Molecular function: aminopeptidase activity; calcium ion binding; protein homodimerization activity; zinc ion binding; peptidase activity
Biological process: peptide catabolic process
Cellular component: apical plasma membrane; membrane
Genetic constraint (gnomAD): Loss-of-function variants: 77 observed, 86.14 expected, observed/expected ratio (o/e) 0.89, 90% interval 0.74 to 1.08. The upper end of that interval is the gene's LOEUF score, 1.08, which puts it in group 4 of 6, group 1 being the genes least tolerant of losing a copy. Missense variants: 956 observed, 975.35 expected, observed/expected ratio (o/e) 0.98, 90% interval 0.93 to 1.03. Synonymous variants: 358 observed, 404.87 expected, observed/expected ratio (o/e) 0.88, 90% interval 0.81 to 0.96.
Homologues: Orthologues: chimpanzee NAALADL1 (99% identical), macaque NAALADL1 (94% identical), pig NAALADL1 (84% identical), mouse Naaladl1 (82% identical), dog NAALADL1 (81% identical), guinea pig NAALADL1 (80% identical), rat Naaladl1 (79% identical), zebrafish naaladl1 (55% identical), Caenorhabditis elegans gcp-2.1 (29% identical), Caenorhabditis elegans gcp-2.2 (29% identical). Paralogues in human: NAALAD2 (38% identical), FOLH1 (38% identical), TFR2 (26% identical), TFRC (24% identical), NAALADL2 (23% identical).
Diseases named in the same sentence as NAALADL1 in open-access papers:
NAALADL1 is named in the same sentence as 6 diseases in open-access papers, as found by Europe PMC text mining. Sharing a sentence is not in itself a finding about the gene and the disease. The quoted sentences say what the papers report.
prostate carcinoma (1 paper, 2023). A carcinoma that arises from epithelial cells of the prostate gland. "NAALADL1 encodes NAALADaseL, which is studied as a biomarker in prostate cancer." (PMID 38066476, 2023).
uterine leiomyosarcoma (1 paper, 2023). "Specifically, genes such as PGR, TRIM22, BOK, NAALADL1, AFAP1L2, and ESR1 showed MSS values greater than 5 in uterine leiomyosarcoma samples." (PMID 38066476, 2023). "In addition, BOK, NAALADL1, and AFAP1L2 were identified as genes with MSS values greater than 5 in uterine leiomyosarcoma samples." (PMID 38066476, 2023).
NAALADL1 also shares sentences with these, for which no sentence is quoted: cancer (1 paper); colorectal cancer (1); infectious disease (1); Tumor (1).